ACKR3 (atypical chemokine receptor 3)
Description:
Atypical chemokine receptor that controls chemokine levels and localization via high-affinity chemokine binding that is uncoupled from classic ligand-driven signal transduction cascades, resulting instead in chemokine sequestration, degradation, or transcytosis. Also known as interceptor (internalizing receptor) or chemokine-scavenging receptor or chemokine decoy receptor. Acts as a receptor for chemokines CXCL11 and CXCL12/SDF1. Chemokine binding does not activate G protein-mediated signal transduction but instead induces beta-arrestin recruitment, leading to ligand internalization and activation of MAPK signaling pathway. Required for regulation of CXCR4 protein levels in migrating interneurons, thereby adapting their chemokine responsiveness. In glioma cells, transduces signals via MEK/ERK pathway, mediating resistance to apoptosis. Promotes cell growth and survival. Not involved in cell migration, adhesion or proliferation of normal hematopoietic progenitors but activated by CXCL11 in malignant hemapoietic cells, leading to phosphorylation of ERK1/2 (MAPK3/MAPK1) and enhanced cell adhesion and migration. Plays a regulatory role in CXCR4-mediated activation of cell surface integrins by CXCL12. Required for heart valve development. Regulates axon guidance in the oculomotor system through the regulation of CXCL12 levels. Acts as a receptor for SHLP2, mediating its effects on activation of proopiomelanocortin neurons in the arcuate nucleus of the hypothalamus which leads to suppression of food intake and increased energy expenditure. (Microbial infection) Acts as a coreceptor with CXCR4 for a restricted number of HIV isolates.
Synonyms: CXC-R7; CXCR-7; RDC-1; CMKOR1; CXCR7; GPR159; RDC1
Tractability: Small molecule: a structure with a bound ligand is known; a high-quality ligand is known; it belongs to a druggable protein family. Antibody: UniProt places it where antibodies can reach, with high confidence; its Gene Ontology location is reachable by antibodies, with high confidence; UniProt predicts a signal peptide or a membrane-spanning region; the Human Protein Atlas places it where antibodies can reach. PROTAC: UniProt records ubiquitination sites on it; ubiquitination databases record sites on it; a small molecule that binds it is known.
Target class: Peptide receptor (family A GPCR); Membrane receptor; Family A G protein-coupled receptor; CXC chemokine receptor; Chemokine receptor
Chemical probes: CHEMBL3581264
Gene: Protein-coding gene on chromosome 2 (236,567,692 to 236,582,358, forward strand). Ensembl gene ENSG00000144476.
Subcellular location: Cell membrane; Early endosome; Recycling endosome
Subcellular location (Human Protein Atlas): Plasma membrane; Vesicles
Pathways (Reactome):
Signal Transduction: Chemokine receptors bind chemokines; G alpha (i) signalling events
Gene Ontology:
Molecular function: C-X-C chemokine binding; C-X-C chemokine receptor activity; protein binding; scavenger receptor activity; C-C chemokine binding; C-C chemokine receptor activity; chemokine binding; coreceptor activity; G protein-coupled receptor activity
Biological process: chemokine-mediated signaling pathway; negative regulation of intrinsic apoptotic signaling pathway in response to DNA damage; oculomotor nerve development; positive regulation of ERK1 and ERK2 cascade; receptor internalization; calcium-mediated signaling; cell chemotaxis; immune response; positive regulation of cytosolic calcium ion concentration; angiogenesis; chemotaxis; G protein-coupled receptor signaling pathway; positive regulation of mesenchymal stem cell migration; vasculogenesis
Cellular component: cell surface; clathrin-coated pit; early endosome; endosome; plasma membrane; recycling endosome; external side of plasma membrane; membrane
Genetic constraint (gnomAD): Loss-of-function variants: 6 observed, 24.08 expected, observed/expected ratio (o/e) 0.25, 90% interval 0.14 to 0.49. The upper end of that interval is the gene's LOEUF score, 0.49, which puts it in group 2 of 6, group 1 being the genes least tolerant of losing a copy. Missense variants: 396 observed, 499.7 expected, observed/expected ratio (o/e) 0.79, 90% interval 0.73 to 0.86. Synonymous variants: 209 observed, 215.44 expected, observed/expected ratio (o/e) 0.97, 90% interval 0.87 to 1.09.
Cancer hallmarks: proliferative signalling (promotes); invasion and metastasis (promotes); invasion and metastasis (suppresses); angiogenesis (promotes); escaping programmed cell death (promotes)
Homologues: Orthologues: chimpanzee ACKR3 (99% identical), macaque ACKR3 (98% identical), guinea pig ACKR3 (94% identical), dog ACKR3 (93% identical), mouse Ackr3 (93% identical), rat Ackr3 (93% identical), pig ACKR3 (90% identical), rabbit ACKR3 (82% identical), tropical clawed frog ackr3 (65% identical), zebrafish ackr3b (54% identical), zebrafish ackr3a (52% identical), Caenorhabditis elegans npr-20 (16% identical). Paralogues in human: CXCR2 (28% identical), CXCR1 (27% identical), CX3CR1 (26% identical), CCR4 (26% identical), CCR7 (26% identical), CXCR3 (25% identical), CCR1 (25% identical), CCR2 (25% identical), CCR9 (25% identical), ACKR4 (25% identical), CCR5 (24% identical), CCR6 (24% identical), and 11 more.
Diseases named in the same sentence as ACKR3 in open-access papers:
ACKR3 is named in the same sentence as 230 diseases in open-access papers, as found by Europe PMC text mining. Sharing a sentence is not in itself a finding about the gene and the disease. The quoted sentences say what the papers report.
breast carcinoma (90 papers, 2008 to 2025). "Similarly CXCL12, a ligand of both CXCR4 and ACKR3, is associated with advanced breast cancer in humans, and is expressed at high levels during puberty and pregnancy in our study (data not shown)." (PMID 27888192, 2017). "In breast cancer, the CXCL12/CXCR4/ACKR3 axis promoted breast cancer metastasis through the activation of the STAT3 pathway." (PMID 38920657, 2024). "Enhanced CXCR4 and ACKR3 levels in breast cancer compared to normal tissues has been reported, although their relative abundance within molecular subtypes and in BC cellular models is unclear." (PMID 36233192, 2022). "We have investigated in cell models representative of the major subtypes of breast cancer (BC) the interplay between the chemokine CXCL12/CXCR4/ACKR3 and EGF receptor (EGFR) family signaling cascades." (PMID 36233192, 2022). "CXCR7, also known as ACKR3, is key in the progression of various tumors including lung, glioma, and breast cancer." (PMID 35430346, 2022). "The CXCL12/CXCR4/ACKR3 cascade is reported to be involved in almost every aspect of breast cancer tumorigenesis." (PMID 36233192, 2022). "Both CXCR4 and ACKR3 signaling pathways promote tumor growth and metastasis in breast cancer and multiple other malignancies, making these receptors potential targets for therapy and molecular imaging." (PMID 35681470, 2022). "Another study indicated that CXCR7/ACKR3 expression by breast cancer cells was down-regulated by MSC-derived CXCL12 (possibly due to ligand-dependent receptor internalization), and under these conditions, metastasis was reduced." (PMID 32582148, 2020). "Along these same lines, it was found that CXCR7/ACKR3 increased the stability of ERα and conferred insensitivity to tamoxifen in luminal-A breast cancer cells." (PMID 32582148, 2020). "Regrettably, ACKR3 can also promote tumor cells survival and high levels of ACKR3 are present in samples from patients with breast cancer." (PMID 33096815, 2020). "It was found that the expression of ACKR3 at protein and mRNA levels in precancerous breast cancer was much higher than that in adjacent and normal breast tissues." (PMID 32253815, 2020). "Healthy endothelial cells show low expression of ACKR3, but it increases in the tumor vasculature in different malignancies including the breast cancer." (PMID 33096815, 2020). "Several studies have shown that the high expression of ACKR3 is positively correlated with the proliferation of breast cancer cells, indicating that ACKR3 has a positive effect on tumor growth." (PMID 32253815, 2020). "The atypical chemokine receptor ACKR3 (CXCR7) is undetectable in normal breast tissues whereas is overexpressed in more than 30% of breast carcinomas." (PMID 31652624, 2019). "ACKR3 (CXCR7) promotes breast cancer cell proliferation and is upregulated here during lactation and involution (data not shown)." (PMID 27888192, 2017). "Of note, ACKR3 preferentially sequesters the monomeric form of CXCL12, whereas dimeric CXCL12 showed significantly lower binding to ACKR3 in vitro and in a breast cancer xenograft model." (PMID 26347749, 2015). "Furthermore, in various tumors, including lung cancer, breast cancer, and colorectal cancer, the activation of the CXCL12/CXCR4/ACKR3 signaling axis has been associated with STAT3 pathway activation." (PMID 38920657, 2024). "Moreover, a role for ACKR3 in tumor neovascularization has been suggested using in vitro models of tube formation with glioma endothelial cells, breast cancer cells or human umbilical vein endothelial cells." (PMID 35008294, 2021). "ACKR3 knockdown in endothelial cells increases the number of circulating tumor cells, recurrence of disease and metastasis suggesting protective role of endothelial ACKR3 in breast cancer against metastasis." (PMID 33096815, 2020). "In breast cancer, ACKR3 has been shown to support scavenging of CXCL12." (PMID 33096815, 2020).
breast carcinoma (continued). "Altered expression of ACKR3 has also been detected in liver, prostate, kidney, and breast cancers." (PMID 31895690, 2019). "Moreover, detrimental actions of ACKR3/CXCR4 dimers have been described in breast cancer." (PMID 33096815, 2020). "Similar results were observed when metastatic breast cancer MDA-MB-231 cells, which express high levels of endogenous ACKR3 and CXCR468, were treated with the ACKR3-targeting nanobodies." (PMID 41330916, 2025). "We used luciferase complementation in cell-based assays and a tumor xenograft model of breast cancer in NSG mice to quantify how CXCR4 and ACKR3 change protein interactions in the β-arrestin-ERK-PKM2 pathway." (PMID 35681470, 2022). "Indeed, in head and neck squamous cell carcinoma patients, ACKR3 expression has been associated with increased lymph node metastasis rate and the relationship between CXCR4 and ACKR3 has also been linked to increased breast cancer metastasis in experimental models." (PMID 35008294, 2021). "Network analysis on the cancer genome atlas (TCGA) breast cancer dataset revealed interaction between CXCL12 and CXCR7 (ACKR3), and a number of G-protein family members (GNG5, GNB4, GNB2, GNG12, GNG7, GNGT1, and GNAI3)." (PMID 30993013, 2019). "We separately observed that both ACKR3 and CXCR4 are overexpressed in breast cancer tumours of two patients with invasive ductal or lobular carcinoma, an increase also observed elsewhere." (PMID 30441765, 2018). "ACKR3, also known as CXCR7, is another atypical receptor binding CXCL12 and CXCL11, and has been shown to regulate breast cancer metastases." (PMID 30591657, 2018). "Besides, ACKR3 was scarcely expressed, and ACKR1 was expressed in a subset of endothelial cells in breast cancer." (PMID 37564657, 2023). "qPCR and flow cytometric analyses were carried out to assess CXCR4 and ACKR3 expression in four breast cancer cell lines, however none expressed both receptors at high levels." (PMID 30441765, 2018). "Initial experiments showed that CXCR4 and ACKR3 were upregulated in primary breast cancer and that CXCR4 and ACKR3 could form heterodimers in transfected CHO cells." (PMID 30441765, 2018). "In breast cancer, some reports suggest that both receptors are found in the same cell, whereas others report that CXCR4 and ACKR3 are found in distinct cell subsets, with uptake of CXCL12 by ACKR3+ BC cells enhancing proliferation and metastatic potential of CXCR4+ cells." (PMID 36233192, 2022).
glioma (51 papers, 2010 to 2025). A benign or malignant brain and spinal cord tumor that arises from glial cells (astrocytes, oligodendrocytes, ependymal cells). "As another example, ACKR3, which is only downregulated in TSPO-deficient BTIC129, prevents TMZ-induced apoptosis in glioma." (PMID 37158962, 2023). "Among them, one gene (CXCR5) was downregulated while five other genes (CXCR1, CXCR2, CXCR3, CXCR4, and ACKR3) were enriched in glioma compared with normal brain tissues." (PMID 35571062, 2022). "It has been reported that Ackr3 transduced signals via “MEK/ERK pathway” to mediate resistance to apoptosis in glioma cells, and it promoted cell growth and survival." (PMID 33479397, 2021). "In contrast, the activity of ACKR3 in glioma cell motility remains elusive and its function in the invasion of other cancer cell types is still a matter of debate." (PMID 35008294, 2021). "The role of ACKR3 in the development of malignant tumors of CNS, including gliomas was also described by various researchers." (PMID 32456359, 2020). "It was revealed that in human gliomas, both mRNA and protein levels of ACKR3 were found to be upregulated in glioma." (PMID 32456359, 2020). "While in grade II gliomas expression of ACKR3 was restricted to tumor cells, in tumor grade III it is present mainly in tumor vascular endothelial cells and only marginally in cancer cells." (PMID 32456359, 2020). "Along these lines, a local increase of membrane pressure in certain cell environments could explain the apparent ability of ACKR3 to activate G proteins in astrocytes and glioma cells." (PMID 40232828, 2025). "On the other hand, there are reports that ACKR3 can activate Gαi/o proteins in astrocytes and glioma cells, hinting that the specific cellular environment could play a role in dictating the bias of ACKR3." (PMID 35857509, 2022). "In glioma cells, ACKR3 expression appears upregulated in hypoxic conditions." (PMID 35008294, 2021). "Additionally, a predominant intracellular localization of ACKR3 expression was shown, with only a slight membrane expression in all glioma cell lines examined." (PMID 32456359, 2020). "However, CXCR4 and ACKR3 expression is not specific to glioma-associated endothelial cells, and both receptors are also detected in endothelial cells from the developing brain or from the adult brain." (PMID 35008294, 2021). "Furthermore, both ACKR3 and Cx43 have been involved in glioma progression." (PMID 32978390, 2020). "In addition, ACKR3 is highly expressed on tumor endothelial, microglial, and glioma cells." (PMID 32456359, 2020). "In addition, it was revealed that endothelial expression of ACKR3 in human glioma may influence the survival prognosis, depending on the IDH classification." (PMID 32456359, 2020). "One report has shown that in cultured primary astrocytes and human glioma cells, CXCL12 induced ACKR3 mediated increases of intracellular calcium and pertussis toxin sensitive ERK and AKT signaling suggesting ACKR3 activates Gi/o." (PMID 34583741, 2021). "This review also highlights ACKR3 as a multifaceted player in almost every of these glioma-related cellular processes and subtypes and prompts researchers in the field to further apprehend the subtleties of the CXCR4/ACKR3/CXCL12 triad in glioma." (PMID 35008294, 2021). "Given the discernible expression of ACKR3 in MVP areas of GBM tumors, its contribution to the angiogenic mechanisms in glioma patients and its interplay with CXCR4 definitely warrant further investigation." (PMID 35008294, 2021). "Interestingly, cellular distribution of ACKR3 in gliomas may differ depending on tumor grade." (PMID 32456359, 2020). "ACKR3, formerly known as CXCR7/RDC1, has also been investigated in glioma patient tissue where its expression pattern appears quite inconstant: several studies highlight an increased mRNA expression in GBM tissue samples compared to non-malignant brain samples, while other studies do not." (PMID 35008294, 2021).
prostate carcinoma (44 papers, 2010 to 2025). A carcinoma that arises from epithelial cells of the prostate gland. "Atypical chemokine receptor 3 (ACKR3), a member of the G protein-coupled receptor (GPCR) superfamily, is widely expressed in a wide range of cancers, particularly in methotrexate-resistant prostate cancer tissue." (PMID 40521034, 2025).
lung carcinoma (34 papers, 2009 to 2025). "Upregulation of ACKR3 was found not only on cancer cells in several malignant tumors, such as prostate, breast, and lung cancers, but also on tumor-associated endothelial cells." (PMID 32456359, 2020). "In lung cancer, the expression of ACKR3 was the most upregulated among chemokine receptors induced by pro-inflammatory TGF-β1 and correlated with shorter patient survival." (PMID 32456359, 2020). "With regard to ACKR3, studies have shown that over expression of ACKR3 promotes lung cancer growth and angiogenesis." (PMID 30257500, 2018). "Like CXCR4, ACKR3 has been considered a potential target for therapy of a number of cancers, including glioblastoma, endometrial carcinoma, and lung cancer." (PMID 29088715, 2017). "According to the results, miR‐100 expression was down‐regulated in primary lung cancer tissues compared to healthy lung tissues in all NSCLC patients, and circ_0072309 and ACKR3 expression were up‐regulated." (PMID 37496297, 2023). "One positive correlation (hsa_circ_0072309 vs. ACKR3) and two negative correlations (hsa_circ_0072309 vs. miR‐100; miR‐100 vs. ACKR3) were observed in the BM samples, primary lung carcinoma foci, and serum samples of BM+ patients (p < 0.0001)." (PMID 37496297, 2023).